CRP (C-reactive protein)
Diseases named in the same sentence as CRP in open-access papers (continued):
Sharing a sentence is not in itself a finding about the gene and the disease.
diabetes (continued). "HIF-1α levels positively correlated with CRP (r = 0.226, P = 0.023), IL-6 (r = 0.316, P<0.001), UKPDS risk score (r = 0.144, P = 0.009), HbA1c (r = 0.242, P<0.001) FBG (r = 0.244, P = 0.029), and CAC scores (r = 0.360, P<0.001), but did not correlate with diabetes duration, age, and LDL." (PMID 24564828, 2014). "The model for CRP contained WC and HOMA-IR, and the model for HOMA-IR contained WC and the interaction between WC and glucose tolerance groups (normal glucose tolerance [NGT], impaired glucose tolerance [IGT] and diabetes mellitus [DM])." (PMID 24681553, 2014). "The results of our study showed that the serum levels of CRP and ESR in AL patients with diabetes were higher than those in AL patients without diabetes." (PMID 41479545, 2025). "Our study identified these parameters as being associated with the severity of AP: etiology nonA-nonB, presence of diabetes mellitus, pain VAS, WBC, and CRP levels." (PMID 40002586, 2025). "Single factor analysis showed that there were significant differences in indicators such as diabetes history, BNP, homocysteine, MHR, NLR, Ang II, and CRP between patients with and without early recurrence (P < 0.05)." (PMID 40454234, 2025). "Third, although major confounders such as age, sex, diabetes, hypertension, and smoking were adjusted for, other potential influences - such as medication use, socioeconomic status, and genetic factors - were not assessed and may have affected CRP levels or outcomes." (PMID 41200636, 2025). "It is worth noting that we found the cut-off value of CAR for diagnosing PJI in patients with diabetes was lower than that in non-diabetic PJI patients (0.134<0.232), and this trend is completely opposite to that of CRP." (PMID 41479545, 2025). "The scoring system includes: Acute kidney injury (AKI), CRP > 50 mg/L, serum albumin < 2.5 g/dL, ascitic fluid protein < 1.0 g/dL, MELD ≥ 15, diabetes mellitus, multidrug-resistant organisms (MDRO), and non-use of β-blockers (each = 1 point)." (PMID 41353185, 2025). "Gender, age, CRP, WBC, lipid levels, history of hypertension, and history of diabetes were not significantly different (P > 0.05) between the two groups." (PMID 38191965, 2024). "BMI, prevalence of diabetes, history of stroke, SQRQ, BODE index, HbA1c and CRP did not significantly differ between the two groups." (PMID 38750572, 2024). "Even in the absence of infection, patients with CVC had significantly higher serum hs-CRP levels than those with AVF independent of sex, race, and diabetes mellitus (DM) status." (PMID 38846514, 2024). "The mean age, CURB 65 and serum biomarkers such as CRP, WBC, NEUT% and the comorbidity rate of hypertension and diabetes mellitus is not significantly different between groups." (PMID 38867204, 2024). "The median C-reactive protein (CRP) in the T2D group was 42 mg/L, and in the group without diabetes, it was significantly lower 24 mg/L (p < 0.0001)." (PMID 38398069, 2024). "Additional adjustments for other risk factors of CKD and neurodegeneration, including hypertension and diabetes (model II) and smoking, BMI, fasting plasma glucose, LDL cholesterol, CRP, and homocysteine (model III) did not alter the statistical significance." (PMID 37225431, 2023). "Patients with LAT were more likely to be male, had diabetes and heart failure, with larger LAD, lower BMI and higher level of C-reactive protein (CRP), than those without LAT." (PMID 37891483, 2023). "Furthermore, some individuals with prediabetes or DM have elevated CRP levels even in the absence of infection." (PMID 38202252, 2023). "Patients with LAT were more likely to be male, and had heart failure and diabetes, with larger LAD and higher CRP levels, than those without LAT." (PMID 36624370, 2023). "In the Insulin Resistance Atherosclerosis Study (IRAS), the odds ratio of nondiabetic subjects with risks of developing diabetes correlated with an increase in PAI-1 and CRP." (PMID 38024366, 2023).
diabetes (continued). "We hypothesised that chronic hyperglycaemia might affect CRP levels because systemic CRP levels progressively increase with progression from euglycaemia to prediabetes to DM in individuals without an infection secondary to low-grade infection." (PMID 38202252, 2023). "In this analysis, CRP reduction was significantly greater with semaglutide compared with placebo in the STEP 1 and 3 trials of people with overweight or obesity without diabetes." (PMID 36467859, 2022). "These associations were independent of lifestyle factors, duration of diabetes, history of CVD, CRP, HbA1c, FBG, lipid parameters, and BMI." (PMID 35548441, 2022). "In univariate analyses, RMSSD and pNN50 were significantly inversely correlated with level of HbA1c and CRP among people with T2DM and pre-diabetes, but not among NGM." (PMID 36289393, 2022). "There were remarkable differences flanked by the AKI set and nongroup in hypertension and diabetes, COPD, eGFR, baseline Scr, BUN, PCT, CRP, HGB, monocyte, MLR, NLR, and PLR." (PMID 36072574, 2022). "After adjusting for age, sex, BMI, WC, HOMA-IR, CRP, FPG, 2hPG, ALT, AST, GGT, hypertension, diabetes, and dyslipidemia, higher NC at baseline was a negative factor for the remission of MAFLD (OR 0.57, 95% CI: 0.40–0.80, p < 0.01)." (PMID 35858581, 2022). "Among diabetes patients with no MCI, the opposite was true, suggesting that an increased CRP level in the circulation can be an early indicator of MCI development in diabetes patients." (PMID 35682821, 2022). "The data showed that hypertension, estimated GFR, in-hospital peak glycemia, peak CK-MB, and C-reactive protein remained as independent predictors of no-reflow after primary PCI in patients with STEMI and diabetes." (PMID 33506051, 2021). "Besides, considering that the well-recognized inflammatory biomarker CRP was not responsive in our study, we also suggest that in menopause plus diabetes low-grade inflammatory background, the serum eHSP72 levels may be more sensitive and a better biomarker of the preclinical stages." (PMID 34568498, 2021). "Our estimated partial Spearman’s correlations show that creatinine and hs-CRP, as well as fasting glucose and insulin, were inversely correlated with 25(OH)D and positively correlated with PTH among individuals without diabetes." (PMID 34531372, 2021). "Inflammatory biomarkers including C-reactive protein (CRP), lactate dehydrogenase (LDH), and erythrocyte sedimentation rate (ESR) were increased in patients with diabetes compared to non-diabetic patients (P < 0.05 for all the comparisons)." (PMID 33746672, 2021). "White blood cell counts and hs-CRP and low-density lipopolysaccharide cholesterol (LDL-c) levels were significantly higher in the diabetes and nondiabetes STEMI groups than in the control group (both P < 0.05)." (PMID 30983881, 2019). "eGFR was not significantly different between those with or without diabetes (median [IQR]: 26.0 [16.5‐37.3] vs 29.1 [17.7‐47.5], P = 0.142), but CRP was higher in those with diabetes (median [IQR]: 3.40 [2.12‐9.51] vs 2.25 [1.08‐4.84], P < 0.001)." (PMID 30358903, 2019). "Adjusted for age, sex, smoking (never, past, and current), hypertension, diabetes, total/HDL cholesterol ratio and education (in years), CRP ≥ 3 mg/l, fibrinogen > median (3.0 g/l)." (PMID 30530864, 2019). "Diabetes status, glycemic control, OSA severity, sleep duration, caloric consumption and timing were not related to hs-CRP." (PMID 30367094, 2018). "Patients with DR had higher levels of HbA1c, Hs-CRP, fasting glucose, HOMA-IR, and diabetes duration than those without DR (P<0.05)." (PMID 30135138, 2018). "There were neither significant differences of age, sex, duration of diabetes, nor hs-CRP or insulin treatment between GADA positive and negative group observed in elderly diabetes." (PMID 29887833, 2018).
diabetes (continued). "Adding other factors including the presence of diabetes, serum creatinine, MDRD-4 eGFR, urinary ACR, serum C-reactive protein (CRP), calcium, phosphate, PTH, RANKL, OPG and MGP did not improve the model significantly." (PMID 28320782, 2017). "The BC-MMSE associations were similar to the main analyses when we excluded men with higher CRP levels and MMSE influential values and outliers (10 men) and when we did not adjust for diabetes, hypertension, and CHD." (PMID 27259001, 2017). "High sensitivity C-reative protein (hs-CRP) is a marker of systemic inflammation and a predictor of incident CVD and CHD, independent of diabetes." (PMID 28435446, 2017). "The etiological agent, the final diagnosis, CRP and PCT levels and the presence of diabetes, COPD or coronary artery disease were not statistically different between survivors and non-survivors." (PMID 27788141, 2016). "In patients without diabetes, lower ABI was related to a higher concentration of CRP and E-selectin, and a lower concentration of HDL-C and eGFR." (PMID 27834825, 2016). "The levels of CRP, IL-6, IL-17, and A-FABP in simple obesity and diabetes with or without obesity groups were obviously increased compared to those in the normal control group (P < 0.05)." (PMID 27819006, 2016). "In patients with PAOD without diabetes, the ABI was related to age, the duration of the symptoms of PAD, the levels of CRP, E-selectin, high-density lipoprotein cholesterol, and the glomerular filtration rate(determination coefficient R2 = 0.844)." (PMID 27834825, 2016). "As there was significantly more type-2 diabetes (DM) in the VA-HIT than in the FOS cohort we also have tested whether DM was a confounder in the distribution of CRP-mfs using subjects with and without diabetes from the VA-HIT cohort." (PMID 25299074, 2014). "C-reactive protein (CRP) is a non-specific marker of inflammation, but is often utilized as a tool in monitoring patients with diabetes and heart disease." (PMID 25515553, 2014). "There are negative effects of diabetes mellitus and hypertension on CAS development in patients with high hs-CRP levels and especially in women." (PMID 24204905, 2013). "There were negative effects of diabetes mellitus and hypertension on CAS development in patients with high hs-CRP levels." (PMID 24204905, 2013). "Most studies for n-3 intake with either CRP or HCY are performed in specific populations, but do not compare across ethnicities and diabetes status." (PMID 31667003, 2013). "Serum levels of CRP, prior to surgery, were significantly higher in the patients with T2DM (39.0±8.3 mg/l) than in those without diabetes (13.8±2.0 mg/l, p<0.01)." (PMID 23119124, 2012). "Candesartan improved plasma HMW-ADN and PAI-1 values but not those of plasma Hs-CRP, VACM-1 and U-8-OHdG in hypertensive patients with type 2 diabetes mellitus of long duration independently of blood pressure changes." (PMID 23034088, 2012). "In contrast, BMI, LDL, waist circumference, CRP, leptin, A-FABP and RBP-4 did not differentiate the types of diabetes." (PMID 22164267, 2011). "The final multivariate models included APOE variants, age, sex, education, ever/never smoking, HDL cholesterol, CRP, triglycerides, TSH, diabetes, hypertension, obesity and albuminuria." (PMID 19852818, 2009). "Trends and significant differences remained for resistin, CRP, insulin and HOMA2-IR among a healthier subgroup of participants that was free from cancer, CVD and diabetes (data not shown)." (PMID 19788754, 2009). "However, multivariate regression analyses demonstrated that neither diabetes mellitus nor hypertension independently predicted serum or salivary PDPN levels, whereas OC status and CRP remained significant." (PMID 41594182, 2026).
diabetes (continued). "The differences in patients’ sex, age, BMI, history of hypertension, history of diabetes mellitus, hepatic encephalopathy, ascites, Child-Pugh score, WBC count, and HB, PLT, ALT, TB, SCr, PT, CRP, PCT, and PNI levels were not statistically significant (p > 0.05)." (PMID 40276743, 2025). "On the one hand, the serum levels of C-reactive protein (CRP) were higher in patients with prediabetes compared to individuals with normal glucose levels, and inflammation was not supplemented after developing diabetes." (PMID 40260278, 2025). "After adjusting for multiple factors, including age, sex, drinking status, smoking status, cancer, CLD, CKD, hypertension, diabetes, HDL, LDL, TC, HGB, CRP, WBC, PLT, HBA1c, CYSC, UA, and eGFR, a non-linear relationship between TyG-WWI and stroke incidence was also observed." (PMID 40667444, 2025). "For example, a patient who is 61 years old with a KPS score of 81, BMI < 24, no diabetes, no targeted therapy, Hb = 121, WBC = 7, LDH = 243, CRP = 34, PLR = 197, and LMR = 3 has 1-year, 2-year, and 3-year survival probabilities of 0.90, 0.62, and 0.32, respectively." (PMID 39635526, 2024). "Compared with patients without AF, patients with NOAF had higher age, c-reactive protein level, larger left atrial diameter (LAD), higher prevalence of male, hypertension, diabetes, coronary heart disease, smoking history, centric pulmonary carcinoma and pericardial effusion (all P<0.05)." (PMID 37519821, 2023). "The best results in terms of CRP reduction were in the T2DM group (from 3.64 to 1.07 mg/L, p = 0.000), and the most modest were in the case of the patients starting off without either diabetes or chronic kidney disease (from 3.96 to 2.72, p = 0.151)." (PMID 38201325, 2023). "There were no statistical differences between the sex in the distribution of physical activity (yes/no), diabetes mellitus (yes/no), family history of ASCVD (yes/no), treatment of hypertension (yes/no), control of hypertension (yes/no) and hs-CRP (all P-value > 0.05)." (PMID 35067842, 2022). "Finally, we did not have data on the treatment or control of diabetes, the presence of other diabetic microvascular complications that may increase LEA risk, or the presence of potential confounders such as hyperlipidemia, C-reactive protein and homocysteine levels." (PMID 34998400, 2022). "In addition, we previously demonstrated the negative effects of diabetes mellitus and hypertension on CAS development in patients with high CRP levels, indicating 2 different vascular pathologies exist in CAS and atherosclerotic cardiovascular disease." (PMID 35096275, 2022). "Furthermore, patients with diabetes more often presented with a NSTEMI; they more often had an impaired kidney function, decreased admission hemoglobin, and higher levels of admission C-reactive protein values compared to patients without known diabetes." (PMID 35532812, 2022). "However, age, hypertension, diabetes, APTT, fibrinogen, TT, blood RBC, hemoglobin, platelets, lymphocytes, monocytes, basophil count, and CRP level were not significantly correlated with disease severity." (PMID 36457866, 2022). "Subgroup analyses were performed based on study arms and showed a significant CRP-lowering effect in placebo-controlled studies (SMD: −0.25; 95% CI: −0.47, −0.03, p = 0.02) but not in diabetes medication-controlled studies (SMD: 0.24; 95% CI: −0.20, 0.68, p = 0.29)." (PMID 36467062, 2022). "Third, a standard oral glucose tolerance test (OGTT) for the diagnosis of diabetes and lean/normal-weight MAFLD was lacking in all patients with normal FBG and HbA1c levels, and waist circumference, HOMA-IR, and Hs-CRP were not available in NAFLD patients diagnosed by ultrasonography." (PMID 36079844, 2022). "In addition, the frequency of diabetes, history of PCI or CABG, and increased high-sensitivity C-reactive protein (hs-CRP) levels was greater among non-survivors than among survivors." (PMID 34845284, 2021).
diabetes (continued). "The mean age, number of smokers, drinkers, rates of diabetes mellitus, hypertension, coronary heart disease, COPD, levels of TGs, TC, HDL-C, LDL-C, CRP, fibrinogen, and levels of D-dimer were not significantly different between ESUS cases and LAA ischemic stroke cases (p > 0.05)." (PMID 35250789, 2021). "In this regard, remarkably higher levels of LDH (509 [437.5-665] vs. 465), CRP (95.8 vs. 88.7) and erythrocyte sedimentation rate (ESR) (46 vs. 36.5) were found in patients with diabetes as compared to the non-diabetic group (P = 0.019 and P = 0.005, respectively)." (PMID 33746672, 2021). "In particular, this score which included PNPLA3 and TM6SF2 genotypes, IR, diabetes, hepatic enzymes and C-reactive protein and it was able to detect NASH with an AUROC of 0.835 (95% CI, 0.776–0.895) and of 0.809 (95% CI, 0.757–0.861) in NAFLD patients with and without diabetes, respectively." (PMID 34680476, 2021). "Furthermore, the serum levels of some inflammation‐related biomarker are much higher compared to those without diabetes, such as IL‐6, serum ferritin, ESR and CRP." (PMID 32233013, 2020). "In the four multivariable clinical models that were generated for comparison—i.e., an age + sex model and an age + sex + diabetes + hypertension + history of CVD + tobacco use model, each one with and without CRP—all variables in each model were significant CVD predictors." (PMID 33276814, 2020). "Our study also suggests that HVA status may be influenced by both non-modifiable (age and sex) and modifiable (BMI, hs-CRP, FBG, physical activity, alcohol consumption, education level, history of diabetes mellitus and hyperlipidemia) factors." (PMID 31422381, 2019). "The sensitivity analysis was carried out for diabetes, hypertension, congestive heart failure, sepsis, mechanical ventilation, CRRT dose, CRP and SOFA score, which revealed that a higher BMI did not reduce the risk of the 28-day mortality rate in critically ill patients." (PMID 31424314, 2019). "In addition, unlike other factors, HbA1c, Hs-CRP, HOMA-IR, and diabetes duration were also identified as VTDR indictors in multivariate analysis." (PMID 30135138, 2018). "Regarding predictors, we found CRP and CD4 count were not predictors of pre-diabetes and diabetes." (PMID 28137307, 2017). "Finally, gender, ANA positivity, nicotine use, hyperlipidemia, diabetes, disease duration, ESR, anti-CCP, SJC, VAS, DAS28 (ESR) and DAS28 (CRP) did not significantly correlate with cfPWV in the adjusted statistical models (all p > 0.05)." (PMID 27104116, 2016). "In our study, we also found that an interaction between regional-specific visceral adipose tissue and systemic inflammation in subjects without established diabetes, with only TAT but not PCF having a pronounced effect on HOMA-IR and hs-CRP through multivariate regression analysis." (PMID 24499326, 2013). "Serum total bilirubin, hs-CRP, SAA and homeostasis model assessment- insulin resistance (HOMA-IR) were documented in 94 subjects with and in 73 subjects without MetS (26 and 54 subjects with type 2 diabetes mellitus (T2DM), respectively)." (PMID 24209691, 2013). "The analysis examines the influence of key variables such as CRP levels (≤10 vs. >10 mg/L), age (18–64 vs. ≥65 years), menopausal status, vitamin D levels (<20 vs. ≥30 ng/ml), and the presence or absence of hypertension (HTN) and diabetes (DM) on these outcomes." (PMID 41445831, 2025). "Participants in Quartile 4 of CRP were more likely to be female, Non-Hispanic White and obese, demonstrated elevated levels of serum uric acid, uACR, triglyceride and LDL, coupled with lower levels of eGFR, and had a higher likelihood of smoking, diabetes and hypertension." (PMID 38281018, 2024).